RAC2 (Rac family small GTPase 2)
Diseases named in the same sentence as RAC2 in open-access papers (continued):
Sharing a sentence is not in itself a finding about the gene and the disease.
glioblastoma (7 papers, 2011 to 2025). The most malignant astrocytic tumor (WHO grade IV). "Silencing of either Rac1, Rac2 or Rac3 also inhibits glioblastoma cell migration and invasion in vitro." (PMID 31514269, 2019). "Rac1, Rac2 and Rac3 promote cell proliferation of glioblastoma cells that form tumor spheres, while these colonies are reduced in number and size by silencing either Rac GTPase." (PMID 31514269, 2019). "In conclusion, not only Rac1 but also Rac2 and 3 are important for glioblastoma tumorigenesis and can serve as the potential therapeutic targets against glioblastoma and its stem-like cells." (PMID 28160553, 2017). "Here we demonstrated that not only Rac1 but also Rac2 and 3 are required for the growth, migration and invasion of glioblastoma stem-like cells." (PMID 28160553, 2017). "In our zebrafish transplantation model, we also observed a role of not only Rac1, but also Rac2 and Rac3 in angiogenesis induced by glioblastoma tumorspheres." (PMID 28160553, 2017). "In summary, Rac2 and 3 along with Rac1 are required for cell migration and invasion in glioblastoma stem-like cells." (PMID 28160553, 2017). "For example, in addition to Rac1, Rac2 and Rac3 knockdown in glioblastoma stem cells showed a dramatic decrease in their invasive and migrative capabilities, confirming that Rac proteins in general do play a crucial and necessary role in the invasion of GBM cells." (PMID 32089990, 2020). "Astrocyte subpopulation B (combined from all three brain regions) is mostly correlated with the mesenchymal glioblastoma gene signature, as the enriched genes in this gene set (e.g., Scpcp1, Rac2, Blcrb, Mrc2, Cd14, and C5ar, among others) are upregulated in this subpopulation." (PMID 30957015, 2019). "Rac1, Rac2 and Rac3 are required for the growth, migration and invasion of glioblastoma cells." (PMID 31514269, 2019). "To examine if Rac2 and Rac3, besides Rac1, also promote the migration and invasion of glioblastoma stem-like cells as they do in normal cells, we used the tumorspheroid cells derived from U251-MG that stably express shRNA or scramble shRNA to perform the cell migration assay using Transwell." (PMID 28160553, 2017). "To investigate whether Rac proteins can serve as therapeutic targets for glioblastoma, especially for GSCs or stemloids, we examined the potential roles of Rac1, Rac2 and Rac3 on the properties of tumorspheres derived from glioblastoma cell lines." (PMID 28160553, 2017). "From these results, we conclude that the influence of Rac2 and Rac3 on the formation and proliferation of glioblastoma-stem like cells is no less than Rac1." (PMID 28160553, 2017). "Although the Rac2 is not expressed in normal nervous tissue, its expression is higher in glioblastoma compared to control tissue, and its overexpression is limited to the mesencymal subtype of glioblastoma." (PMID 28160553, 2017).
prostate carcinoma (7 papers, 2012 to 2025). A carcinoma that arises from epithelial cells of the prostate gland. "Downregulation of KBTBD7 was demonstrated to inhibit cell proliferation and invasion of non-small cell lung cancer cells in vitro and small interfering RNA-mediated knockdown of RAC2 demonstrated antiproliferative and proapoptotic effects in prostate cancer cells." (PMID 36671500, 2023). "In contrast, incubation of prostate cancer cells with EPA and DHA reduced the protein expression of GTPases (rac1, rac2 and cdc42) (abstract only)]." (PMID 25971815, 2015).
glioma (6 papers, 2015 to 2025). A benign or malignant brain and spinal cord tumor that arises from glial cells (astrocytes, oligodendrocytes, ependymal cells). "In our in-house cohort, the expression levels of CD274, HMGB2, RAC2, RIN3, and SOD3 were elevated in WHO grade IV gliomas compared to grades II/III." (PMID 40852729, 2025). "Each one of the two correlation coefficients manifested that both SPP1 and HMOX1 were consistently co‐expressed with 20 genes in glioma samples, such as VAMP8, RAC2, MSR1, CAPG and FBP1." (PMID 40495644, 2025). "This includes effects on cell invasion (RAC1, RAC2, RAC3, RHOA, RHOC), focal adhesion formation (RHOA), stemness of glioma precursor cells (RAC1), cell proliferation (RAC1, RND3) and cell cycle (RND3)." (PMID 26132659, 2015). "Seven Rho GTPases (RND1, RND3, RAC3, RHOA, RAC2, RAC1 and RHOC) showed a significantly greater connectivity in grade IV glioma and seven (CHP, RHOD, RHOF, RHOB, RHOQ, RND2, RHOBTB3) showed greater connectivity in grade II glioma." (PMID 26132659, 2015). "Our data indicated that the Wnt pathway activation related genes such as CCN4, FOSL1, LGR6, MMP7, RAC2, SERPINF1 and TCF7 were upregulated, while Wnt pathway inactivation related gene such as CXXC4 was downregulated in radiotherapy treated glioma patients from TCGA database." (PMID 34852024, 2021). "Notably, IMPA2, SOD3, CD274, ITPRIPL1, and RAC2 displayed relatively negative correlations across multiple cancers, including glioma." (PMID 40852729, 2025).
hepatocellular carcinoma (6 papers, 2017 to 2025). A malignant tumor that arises from hepatocytes. "In liver cancer cells, AFAP1‐AS1 can promote the progression of hepatocellular carcinoma by upregulating the positive Rho/Rac2 signaling pathway." (PMID 37916733, 2024). "RAC2, a small GTPase belonging to the Rho family, takes a crucial part in the regulation of cell motility, proliferation and survival, and takes a crucial par in the metastasis of hepatocellular carcinoma and other cancers through cell migration." (PMID 39098994, 2024). "Overall, AFAP1-AS1 may promote NPC and hepatocellular carcinoma metastases through RhoA/Rac2 signaling." (PMID 29618386, 2018). "In addition, a long noncoding RNA was shown to indicate a poor prognosis of hepatocellular carcinoma via upregulation of RhoA/Rac2 signaling." (PMID 28029655, 2017). "RAC2 has been identified as a prognostic biomarker in clear-cell renal carcinoma, while PTTG1 has shown potential as a prognostic indicator in hepatocellular carcinoma due to its role in promoting β-catenin stabilization." (PMID 40072059, 2025).
neuroblastoma (6 papers, 2012 to 2024). Neuroblastoma (NB) is the most common solid, extracranial childhood tumor. "In a syngeneic neuroblastoma (9464D) model, Rac2-deficient mice exhibited significantly reduced tumor growth, suggesting the contribution of M2 macrophages to tumor progression." (PMID 38087370, 2023). "Finally, inhibition of P-Rex1 may be a particularly advantageous novel therapeutic strategy in neuroblastoma given its association with the Rac2 effector." (PMID 38884093, 2024). "This is consistent with data suggesting that Rac2 is specifically produced by hematopoietic cells, and suggests an interplay between neuroblastoma cells and their surrounding tumor microenvironment in modulating Rac2 expression within tumors." (PMID 38884093, 2024). "Potential therapeutic strategies involving Rac2 inhibition, using inhibitors like NSC23766, wortmannin, and LY294002, warrant further exploration in neuroblastoma cancer development." (PMID 38087370, 2023). "Rac2 is a hematopoietic GTPase and our studies have shown that macrophage deletion of Rac2 blocks tumor growth in syngeneic NB9464 model of neuroblastoma." (PMID 32983125, 2020). "Low levels of Rac2 were detected in HeLa and neuroblastoma cells, indicating that it is not exclusively expressed in hematopoietic cells." (PMID 22916134, 2012).
Clear Cell Renal Cell Carcinoma (5 papers, 2021 to 2025). "High RAC2 expression is associated with higher clinical and pathological grade and poorer prognosis in patients with clear cell renal cell carcinoma (ccRCC)." (PMID 40072059, 2025). "High expression of Rac2 may be a diagnostic index for clear-cell renal cell carcinoma, as the knockdown of Rac2 in vitro attenuates the proliferation, migration, and invasion of renal carcinoma cells." (PMID 33995034, 2021). "The analysis of the data from Cancer Genome Atlas Kidney Renal Clear Cell Carcinoma (TCGA-KIRC) showed that RAC2 is significantly upregulated in clear cell renal cell carcinoma (ccRCC)." (PMID 40072059, 2025). "Studies have found that RAC2 can be used as a biomarker for the prognosis of renal clear cell carcinoma and promote the progression of renal clear cell carcinoma." (PMID 34735495, 2021).
lung carcinoma (5 papers, 2016 to 2024). "We identified RAC2 and CDA as genes with significantly higher expression in PD-L1-high lung cancer cell lines." (PMID 27846317, 2016). "Another RAC GTPase and catalytic subunit of NADPH oxidase, RAC2, has also been described to promote transcriptional activation of JUNB in lung cancer (Figure 3iii), which could be yet another mechanism that leads to NFIX activation." (PMID 36901722, 2023).
ovarian carcinoma (5 papers, 2017 to 2025). A malignant neoplasm originating from the surface ovarian epithelium. "In ovarian cancer, upregulation of RAC2 is associated with the formation of NETs and poor prognosis of ovarian cancer, and NET‐associated markers are reliable for ovarian cancer prognosis prediction and treatment evaluation." (PMID 40059806, 2025). "Interestingly, based on our previous results, RAC2 expression was increased in ovarian cancer." (PMID 37214785, 2023).
osteosarcoma (4 papers, 2017 to 2023). A usually aggressive malignant bone-forming mesenchymal neoplasm, predominantly affecting adolescents and young adults. "This study provides the clinical insight that chemokine signaling pathway genes (CCL21, CCL22, CCL24, CXCL11, CXCL12, CXCL13, GNAI2, and RAC2) in proliferating cells might be the potential biomarkers for treatment of osteosarcoma." (PMID 37537613, 2023). "In addition, studies have found that knocking down RAC2 can inhibit the progression of osteosarcoma by inhibiting the wnt signaling pathway." (PMID 33785008, 2021).
viral infection (4 papers, 2023 to 2026). "Interestingly, the heterozygous activating mutation of RAC2 leads to infantile-onset combined immunodeficiency as well as viral infection susceptibility." (PMID 37063865, 2023). "Persistent viral disease with oncogenic complications, bronchiectasis, lymphoproliferation, or progressive organ involvement should prompt consideration of RAC2 testing even beyond infancy." (PMID 41685306, 2026). "These include DOCK2, which is known to activate RAC1/RAC2 genes required for implantation, and TRIM25, a gene involved in innate immune response against viral infection, mediating estrogen action and whose downregulation during embryogenesis in medaka has been shown to result in apoptosis." (PMID 37789509, 2023).
acute myeloid leukemia (3 papers, 2017 to 2021). Acute myeloid leukemia (AML) is a group of neoplasms arising from precursor cells committed to the myeloid cell-line differentiation. "Moreover, Rac2 was shown to be associated with a poor prognosis in patients with systemic mastocytosis and acute myeloid leukemia." (PMID 28029655, 2017).
asthma (3 papers, 2021 to 2025). "The expression levels (the staining intensity) of ITGB2, RAC2 and Vav1 were higher in the asthma group than other groups." (PMID 34618857, 2021). "The levels of most proteins (ITGAM, ITGB2, MMP12, NCF1, NCF2, NCF4, RAC2 and Vav1) were higher in the asthma condition (shown in red) than those in the control condition or after SCIT condition." (PMID 34618857, 2021). "While allergic features were slightly less frequent in the RAC2 GTPase patients (52.8%, particularly with asthma diagnosis), 35.3% of the individuals displayed at least one lymphoproliferative manifestation, which was significantly higher than that of the other groups (p = 0.001)." (PMID 40860338, 2025). "Moreover, RAC2 is important for eosinophils to migrate and release cytotoxic mediators during asthma." (PMID 34618857, 2021). "Specifically, it has been hypothesized that the downregulation of both genes could activate Cdc42 and Rac2 GTPases, promoting the migration of neutrophils and T lymphocytes into the lung, triggering inflammation, a mechanism that could also take place in asthma." (PMID 34442380, 2021). "Defects in RAC2 regulators of actin are usually diagnosed late due to a normal immune profile, but a higher rate of specific viruses (EBV and HPV), gastrointestinal autoimmunity, asthma, and lymphoproliferation compared to CDC42 regulatory defects." (PMID 40860338, 2025).
chronic myeloid leukemia (3 papers, 2018 to 2025). "For instance, in chronic myeloid leukemia (CML) stem cells, Rac2 GTPase alters mitochondrial function, leading to high ROS production through the mitochondrial respiratory chain complex III (MRC-cIII)." (PMID 40214466, 2025). "In the case of chronic myeloid leukemia (CML), Rac2 directly interacted with mitochondrial proteins, thereby ensuring the survival of these cells." (PMID 30558116, 2018).
gastric cancer (3 papers, 2016 to 2025). A primary or metastatic malignant neoplasm involving the stomach. "The qPCR validation showed that PTPRC, SERPINB9, and RAC2 had low expression in gastric cancer cells, whereas only CCL20 and BANK1 were highly expressed." (PMID 40444282, 2025). "Furthermore, we found that NKX6.3 functions as a negative transcriptional regulator of RhoA, Cdc42, Rac1, Rac2, Skp2 and c-Myc genes and completely inhibits c-Myc-p300/CBP-Skp2-Miz1 and Max complex formation, thereby preventing gastric cancer cell migration and invasion." (PMID 27333045, 2016).
leukocyte adhesion deficiency (3 papers, 2017 to 2024). Leukocyte adhesion deficiency (LAD) is a primary immunodeficiency characterized by defects in the leukocyte adhesion process, marked leukocytosis and recurrent infections. "We used a zebrafish model of leukocyte adhesion deficiency in which neutrophils express a dominant negative Rac2 D57N mutation that results in impaired neutrophil recruitment to localized infection." (PMID 28658259, 2017). "Interestingly, the phenotype was predicted by a mouse knockout of Rac2 and resembles leukocyte adhesion deficiency (LAD)." (PMID 33126517, 2020). "Dominant negative mutations in RAC2 result in a phenotype resembling leukocyte adhesion deficiency with an impaired oxidative burst, as RAC2 is not only crucial for NADPH oxidase but also controls cytoskeleton formation and cell adhesion." (PMID 39005504, 2024).
nasopharyngeal carcinoma (3 papers, 2018 to 2024). A carcinoma arising from the nasopharyngeal epithelium. "Our research group has found that the lncRNA AFAP1-AS1 leads to the loss of stress fiber formation in nasopharyngeal carcinoma by influencing the expression of RhoA/Rac2 signaling and F-actin polymerization." (PMID 29618386, 2018). "LncRNA AFAP1-AS1 resulted in a loss of stress fiber formation in nasopharyngeal carcinoma (NPC) via affecting F-actin polymerization, as well as RhoA/Rac2 signaling pathway." (PMID 34290983, 2021).
pulmonary fibrosis (3 papers, 2014 to 2021). Chronic progressive interstitial lung disorder characterized by the replacement of the lung tissue by connective tissue, leading to progressive dyspnea, respiratory failure, or right heart failure. "Rac2 deficiency protected Rac2−/− mice from bleomycin-induced pulmonary fibrosis and resulted in lower mortality compared to wildtype mice." (PMID 33011741, 2021). "If so, we would predict that the injection of WT M2 macrophages and not WT M1 macrophages into Rac2-/- mice would restore the bleomycin induced pulmonary fibrosis susceptibility and rescue the lung fibrosis defect observed in the Rac2-/- model in vivo." (PMID 28817691, 2017). "For the studies described here we hypothesized that Rac2 deficiency protects mice from bleomycin-induced pulmonary fibrosis." (PMID 24970330, 2014). "Taken together, these results demonstrate that the injection of WT M2 macrophages is necessary and sufficient to reverse the bleomycin induced pulmonary fibrosis defect in Rac2-/-." (PMID 28817691, 2017). "In the present study, we investigated the mechanism by which Rac2 regulates fibrogenesis in a bleomycin induced model of pulmonary fibrosis." (PMID 28817691, 2017). "Using a murine model of experimental pulmonary fibrosis, we demonstrated that the presence of Rac2, specifically in the macrophages, promotes increased lung injury and collagen deposition." (PMID 28817691, 2017). "Our data indicate that expression of Rac2 skews lung macrophages toward an alternatively activated profibrotic phenotype, which promotes collagen production, leading to the progression of experimental pulmonary fibrosis." (PMID 28817691, 2017). "Since Rac2 is expressed in a number of hematopoietic lineages and in endothelial cells, we sought to determine if the pulmonary fibrosis defect noted in the Rac2-/- mouse model could be ascribed to a macrophage autonomous M2 dependent phenomenon." (PMID 28817691, 2017). "Our results clearly establish a requirement for Rac2 in bleomycin induced lung fibrosis." (PMID 28817691, 2017). "Taken together, these studies define an important role for an integrin-driven Rac2 signaling axis in macrophages, and reveal that Rac2 activation is required for polarization of macrophages towards a profibrotic phenotype and progression of pulmonary fibrosis in vivo." (PMID 28817691, 2017). "To determine the role of Rac2 in pulmonary fibrosis we used a bleomycin-induced mouse model." (PMID 24970330, 2014). "Our studies suggest that Rac2 provides the signaling specificity to drive the M2 macrophage phenotype under conditions of inflammation where macrophages are interacting with the provisional extracellular matrix and this pathway is required for the development of lung fibrosis." (PMID 28817691, 2017).
colitis (2 papers, 2013 to 2021). Inflammation of the colon. "Our findings demonstrate that a genetic deficiency in Rac2 leads to worsened disease in mice infected with C. rodentium as evidenced by increased clinical symptoms score, colonic epithelial hyperplasia and colitis." (PMID 23613889, 2013). "Our findings demonstrate that Rac2-deficient mice subjected to an infection-based model of colitis develop worsened disease characterized by increased and protracted colonic epithelial cell hyperplasia and exacerbated colonic inflammation." (PMID 23613889, 2013). "To investigate the impact of a Rac2-deficiency on intestinal immune responses and the development of colitis, we subjected WT and Rac2−/− mice to a model of C. rodentium induced colitis." (PMID 23613889, 2013). "Given Rac2’s importance in various fundamental immune cell processes, we investigated whether a defect in Rac2 may impair host immune responses in the intestine and promote disease in the context of an infection-based (Citrobacter rodentium) model of colitis." (PMID 23613889, 2013). "Previous studies have revealed that Rac2 deficiency could result in exacerbated and protracted colitis in response to C. rodentium infection while mice deficient in gp91phox or p47phox displayed no overt differences during acute dextran sulfate sodium (DSS) colitis." (PMID 33780601, 2021).
colorectal cancer (2 papers, 2024 to 2025). A primary or metastatic malignant neoplasm that affects the colon or rectum. "It regulates circRNA (circ_0102913), which is overexpressed in colorectal cancer, sequesters miR-571, and modifies the expression of Rac family small GTPase 2 (RAC2) mRNA." (PMID 39791162, 2025).
COVID-19 (2 papers, 2023 to 2024). A disease caused by infection with severe acute respiratory syndrome coronavirus 2. "While RAC1 and RAC2 share a redundant role at later stages of T-cell development, RAC1 is downregulated in COVID-19 patients with mild symptoms compared to healthy subjects." (PMID 37063865, 2023). "Four DEPs (RAC1, CAMK2G, DAAM1, and RAC2) were enriched in the noncanonical Wnt pathway and two DEPs (TLE3 and CACYBP) were enriched in the canonical pathway in the COVID-19 comparison group." (PMID 39301288, 2024).